IL6 (interleukin 6)
Diseases named in the same sentence as IL6 in open-access papers (continued):
Sharing a sentence is not in itself a finding about the gene and the disease.
tumor (continued). "Recent studies reported that CAFs associated to incipient neoplasia are able to exhibit a pro-inflammatory signature, characterized by an over-expression of SDF-1, IL-6, and IL-1β that contribute to the recruitment of pro-angiogenic macrophages sustaining tumor growth." (PMID 25072019, 2014). "Moreover, we found significantly higher STAT3 phosphorylation in high IL-6-producing tumor tissues than that in low IL-6-producing tissues." (PMID 24789104, 2014). "The association with elevated CRP levels and a dismal prognosis might reflect the prognostic value of tumor produced interleukin-6, an inducer of CRP production in the liver." (PMID 24885814, 2014). "Importantly, these hypoxia and IL6-induced M2 macrophages were more effective at promoting LLC tumor metastasis, suggesting the tumor-promoting effect of macrophages was also enhanced during the tumor hypoxia." (PMID 25313135, 2014). "The ability of IL-6 to inhibit tumour cell growth has been suggested." (PMID 26316944, 2014). "IL-6 treatment also upregulated BMX and pSTAT3 proteins in both infected and uninfected samples, The bone marrow X-linked kinase (BMX) is enriched in GSC compared to astrocytes and neural progenitor cells, and BMX knockdown suppresses tumor growth." (PMID 25549333, 2014). "In tumor-bearing state, G-CSF/IL-6 could endow neutrophils with protumor potential by inducing the enhanced activation of STAT3 and attenuating the activation of PI3K and p38 MAPK pathways in response to T-sMs." (PMID 25587026, 2014). "Moreover, IL-6-induced MDSC recruitment provides a microenvironment conducive to tumor growth and the development of treatment resistance." (PMID 25238263, 2014). "An increased expression of IL-6 has been found in patients with cancer, in serum and tumor tissue." (PMID 25202430, 2014). "In addition, changes on the periovarian fat weights and serum IL-6 levels were also detected with the thicknesses of deposited periovarian adipose tissue and their mean diameters to monitor the tumor-related anticachexic effects." (PMID 25477992, 2014). "In addition, we identified IL-6, a known pleiotropic cytokine, as a principal mediator for the tumor-promoting activity of s-UCMSCs by induction of STAT3 phosphorylation." (PMID 25419563, 2014). "Inhibition of IL-6 signaling may suppress growth, survival, and/or metastatic potential of tumor cells." (PMID 24415766, 2014). "Also, there is evidence that IL-6 directly induces tumor growth and spread after triggering the canonical JAK/STAT pathway, an SHP-2 driven Ras-Raf-MAPK signaling pathway and angiogenesis." (PMID 24886605, 2014). "Indeed, IL-6 silencing specifically in the vascular endothelial cells was sufficient to significantly slow down xenograft tumor growth." (PMID 24533454, 2014). "Furthermore, our data also demonstrated that a high density of TAMs expressing IL-6 and IL-8 was positively correlated with tumor stage." (PMID 24885636, 2014). "According to some reports, TLR engagement leads to production of pro-inflammatory factors such as IL-12, IL-6 and nitric oxide by tumor cells and results in their resistance to cytotoxcicity and apoptosis, increased invasiveness, chemoresistance and tumor growth." (PMID 24966802, 2014). "Since this effect was not seen in the CD16/32+ populations, IL-15 may be important in regulation of IL-6 in T cells or other CD16/32− cells in the tumor microenvironment." (PMID 24416335, 2014). "IL-6 mRNA levels were equivalent to benign and only higher than tumor in lin-CD49f−CD24−cells." (PMID 25269750, 2014). "IL-6 may facilitate angiogenesis, vascularization and tumorigenicity, and may have an important role in tumor progression." (PMID 25109274, 2014). "Furthermore, ZNF300 induces the NF-kB pathway, in turn inducing IL-6 and IL-8, potentially exacerbating inflammation and promoting tumor metastasis." (PMID 24393131, 2014). "These experiments suggest that MUC2 knockdown enhanced IL-6 secretion and promoted tumor growth." (PMID 25322805, 2014).
tumor (continued). "The expression of NF-κB in the tumor tissues was in the same change pattern as IL-6." (PMID 25093140, 2014). "Furthermore, the STAT3 activity in tumor cells enhances the expression of several immune-suppressing soluble factors, such as IL-6, IL-10 and VEGF, all of which are known to prevent the maturation of dendritic cells." (PMID 24995504, 2014). "Immunofluorescence staining was performed to check IL-6 levels of pre-irradiated tumor beds." (PMID 25181290, 2014). "The expression of IL-6 and NF-κB proteins in the tumor tissues was examined with western blotting." (PMID 25093140, 2014). "We found that IMC from atherosclerotic Apo E−/− mice secreted significantly high level of IL-6 compared with the counterparts from tumor-bearing mice, and the serum level of IL-6 was significantly down-regulated by depletion of IMC in atherosclerotic Apo E−/− mice." (PMID 25269085, 2014). "Because IL-6 is mainly derived from fibroblasts, macrophages and endothelial cells, high IL-6 levels in the tumor microenvironment might reduce the tumor response to afatinib." (PMID 24675568, 2014). "Interleukin-6 (IL-6) and interleukin-8 (IL-8) may influence tumor response to therapy but expression in BCSCs is also unknown." (PMID 25269750, 2014). "However, PGE2 alone cannot induce stem cell phenotype and IL-6 secreted by tumor-derived fibroblasts play a key role in the expansion of aggressive stem cell subpopulation." (PMID 25343626, 2014). "Collectively, these results demonstrate that IL-6 secreted by endothelial cells enhance tumor growth, and suggest that cancer patients might benefit from targeted approaches that block signaling events initiated by endothelial cells." (PMID 24533454, 2014). "Our study which compared co-culture with mono-culture demonstrated that tumorigenic effects of HOXB9 in the microenvironment resulted in the enhanced release of various cytokines and that IL6 release from tumor microenvironment plays an important role in tumor proliferation." (PMID 24885802, 2014). "In addition, NF-κB-dependent inflammatory cytokines such as IL-6, TNF-α, and CXCL1/KC have been linked with the enhanced immunosuppressive activity of tumor-infiltrating MDSCs." (PMID 25514597, 2014). "A 5 Gy-irradiation led to increased IL-6 levels in the tumor bed and infiltration of immune cells." (PMID 25181290, 2014). "In addition, it contains bivalent extracellular factors (i.e., IL6) that regulate keratinocyte mitogenesis and the engagement of inflammatory responses during the tumor promotion phase." (PMID 23935450, 2013). "Furthermore, progression and chemoresistance also appear to involve IL-6, NF-κB induced expression of IL-6 by its regulation of the growth and survival of tumor cells." (PMID 23117246, 2013). "Also Listeriaat-Mage-b reduced the production of IL-6 significantly in the tumor primary tumors, but IL-6 production was even more reduced by the combination of Listeriaat-Mage-b and curcumin." (PMID 24156030, 2013). "Comparison of TNF-α and IL-6 levels in the serum of tumor-bearing mice." (PMID 24225772, 2013). "Furthermore, we confirmed that IL-6 trans-signaling was an important mechanism supported by tumor-infiltrating MDSCs to drive the metastatic behavior of cancer cells in vitro and in vivo." (PMID 24021059, 2013). "Chemokines such as CCL2 and CCL4 could help recruit transferred T cells to the primary tumor site and thereby prevent tumor recurrence, and inflammatory cytokines like IL-6 can promote effector T cell infiltration of distant tumor sites." (PMID 23935927, 2013). "Comparison of the secretory factors expressed by CAFs and normal fibroblast revealed that MCP-1, RANTES, VEGF, IL-6 and IL-8 may individually or collectively activate these pathways to induce tumor cell proliferation." (PMID 23922669, 2013). "The IL-6 silencing vector increased expression of E-cadherin associated with decrease in vascular endothelial growth factor (VEGF) and matrix metallopeptidase 9 (MMP-9) expressions in tumor cells." (PMID 23637926, 2013).
tumor (continued). "Therefore, we further examined the link between MDSC and circulating IL-6 in tumor relapse post-irradiation." (PMID 23806095, 2013). "In the tumor-bearing mice, the levels of IL-6, G-CSF and KC were elevated." (PMID 24278103, 2013). "In the tumour setting, we hypothesize that IL6 contributes to increased Ret expression, and Ret in turn helps maintain IL6 expression, thereby forming a positive feed-forward loop." (PMID 23868506, 2013). "Myeloid antigen-presenting cells and cytokines such as IL-2, TGF-β, IL-1, IL-23, and IL-6 may initiate Treg polarization into Th17-like cells in these tumor contexts (147–, 149)." (PMID 23986759, 2013). "PKCζ could be considered a tumor suppressor, though other studies have elucidated functional contributions of the connection of PKCζ to NF-κB and Stat3/IL-6 in carcinogenesis." (PMID 24062985, 2013). "Interestingly, the tumor spheroid (3-D) conditioned media contained significantly higher concentrations of both IL-6 and TNF-alpha than that of healthy donor plasma." (PMID 23372803, 2013). "EMT6_IL-6 cells showed increased tumor growth compared to the control EMT6_Con cells." (PMID 24021059, 2013). "On the other hand, cytokines of TGF-β, IL-6 and IL-23 could promote the development of Th17 cells, which could enhance the immune response in the tumor environment and inhibit tumor growth." (PMID 23587428, 2013). "Based on these data, we hypothesize that tumor-induced autocrine IL-6 production might play a role in regulating miR-17, miR-20a, and thereafter HIF-2α expression in TAMs." (PMID 24194900, 2013). "Immunotherapy with anti-tumor cell antibodies may be improved by lenalidomide, which enhances activation of NK cells and inhibits their suppression by IL-6 and TGFβ1." (PMID 23982484, 2013). "Metastasizing, but not non-metastasizing, tumor-derived factors induced MDSCs to increase IL-6 production and full activation of recruited MDSCs occurred in the primary tumor site and metastatic organ in the vicinity of metastasizing cancer cells, but not in lymphoid organs." (PMID 24021059, 2013). "Compared with control group, IL-6 and G-CSF were elevated about 2-fold in tumor group." (PMID 24278103, 2013). "IL-6 activates target genes involved with differentiation, survival, apoptosis and proliferation, and it plays important roles in pro- and anti-inflammatory functions, acute phase and immune responses in the organism, and tumour progression." (PMID 23384097, 2013). "IL-6 was defined as a crucial factor for tumor survival and immune evasion, i.e., via induced secretion of IL-10 by regulatory T cells, which effectively suppresses adaptive immune responses towards tumor antigens and induces proliferation of immature myeloid cells." (PMID 23616009, 2013). "These cells are T lymphocytes: tumor cell-derived IL-6, interleukin-1 (IL-1), and TGF-β can drive T-cell differentiation towards a Th17 secretory helper-cell phenotype capable of inducing RANKL production by OBs and OC activation through interleukin-17 (IL-17) production." (PMID 23710201, 2013). "In our case, in addition to the elevated serum IL-6 level, the confirmation of IL-6 in tumor cells from a biopsy specimen by immunostaining may have provided evidence for IL-6 production by tumor cells." (PMID 23710188, 2013). "As increased IL-6 trans-signaling in 4T1 cell-bearing mice was suggested to occur in the primary tumor sites and metastatic lung, we evaluated whether increased IL-6 trans-signaling in the lung also affected the efferent phase of cancer cell metastasis." (PMID 24021059, 2013). "Recent scientific literature suggests that IL-6 plays a role also in NB tumor progression." (PMID 24204677, 2013). "Interleukin-6 (IL6), a multifunctional cytokine, may contribute to tumor cell proliferation and differentiation." (PMID 23762858, 2013). "Further investigation of the underlying mechanism revealed simvastatin could exert the anti-tumor effects by suppressing IL-6-induced phosphorylation of JAK2 and STAT3." (PMID 23690956, 2013).
tumor (continued). "Moreover, the MF suppressed tumor-induced production of IL-6, G-CSF and KC, and enhanced the level of IL-12." (PMID 24278103, 2013). "MC-released TNF-α, IL-1, and IL-6 inhibit tumor growth and angiogenesis in melanoma." (PMID 23577028, 2013). "We crossed IL-6-/- mice with KrasG12D mutant mice, which develop lung tumors after activation of mutant KrasG12D, to investigate whether IL-6 inhibition contributes to tumor progression and survival time in vivo." (PMID 24260500, 2013). "We have investigated if berberine could inhibit STAT3 activation in NPC cells by exogeneous stimulus, IL-6, which is commonly secreted by inflammatory stroma cells present in tumor microenvironment." (PMID 24380387, 2013). "Furthermore, we have also established that IL-6 was consistently upregulated in PDT-treated cells, and their levels were associated with increased tumor cell apoptosis and caspase activities." (PMID 23807226, 2013). "Tumor growth and invasive capability were attenuated when IL-6 was blocked." (PMID 23637926, 2013). "A reduction in the level of EI24 induces the expression of the inflammatory cytokines IL-6 and IL-8 that are implicated in tumor malignancy in ZR-75-1 cells, which do not intrinsically express these cytokines." (PMID 24280371, 2013). "The change of post-operative IL-6 and lymphocyte subsets reflected beneficial effects of ulinastatin on anti-inflammatory action, postoperative immunosuppression, and postoperative anti-tumor response." (PMID 23575450, 2013). "In addition, we demonstrated that SASP includes factors that are known to be associated with aggressive cancer cells, including IL-6 and MMP which can induce epithelial cell invasion or direct tumour promoting effects respectively." (PMID 24116215, 2013). "In univariate and multivariate analyses, poor treatment response, no tumor resection, and positive IL-6 staining were significantly associated with shorter survival." (PMID 23561329, 2013). "IL-17 then promotes tumor growth through IL-6 induction, which in turn activates Stat3 in tumors." (PMID 24453427, 2013). "To determine whether tumor proliferation is affected by IL-6 deletion in vivo, we measured BrdU-labeling cells in lung tumors." (PMID 24260500, 2013). "Although these in vitro studies clearly support corticosterone- and NORA-induced increased expression and secretion of IL-6 by B16-F10 cells, it is unclear if the same mechanisms are operating in the complexity of pathophysiological conditions in tumor-bearing mice." (PMID 23517603, 2013). "Furthermore, using xenograft tumors model, inhibition of IL-6 resulted in slower tumor growth in vivo." (PMID 23637926, 2013). "Furthermore, CD68+ tumor-associated macrophages (TAM) coexpressing IL-6 were identified, and CD33+ myelomonocytic cells also expressing IL-6 were detected in metastatic bone marrow samples." (PMID 23805414, 2013). "In addition to this known pro-tumorigenic activity, our data uncovered a pro-metastatic role of paracrine IL-6 in the tumor microenvironment, which facilitates cancer cell migration and invasion." (PMID 23977098, 2013). "Also included is the expectation that the transfer of these oncogenes to a background that is genetically deficient for AID (activation-induced cytidine deaminase) blocks IL-6/BCL-2-driven tumor development at the IgM+ stage." (PMID 24106612, 2013). "IL-17 then promotes tumor growth through Stat3 activation dependent on IL-6 induction." (PMID 24453427, 2013). "In addition to tumor-derived IL-6 autocrine signaling, paracrine IL-6 signaling within tumor microenvironments has been highlighted recently." (PMID 24021059, 2013). "Nguyen and coworkers observed that activation of STAT3 signaling in tumor cells or in inflammatory immune cells modulates secretion of various inflammatory factors such as IL6 and TNFα that act as an immunosuppressors, and increase the probability of survival of tumor cells." (PMID 24199193, 2013).
tumor (continued). "Moreover, this MF suppressed tumor-induced production of cytokines including interleukin-6 (IL-6), granulocyte colony- stimulating factor (G-CSF) and keratinocyte-derived chemokine (KC) (n = 9–10, p<0.05 or 0.01)." (PMID 24278103, 2013). "The production of pro-inflammatory cytokines, IL-1β, IL-6, and TNFα, all of which facilitate tumor growth, in the tumor microenvironment might be due to STAT3 hyperactivation in both the tumor and immune cells." (PMID 23730621, 2013). "However, four tumor-derived cytokines (IL-6, IL-8, TNF-α, and IFN-γ) were found time-dependently induced in the SiHaparental group." (PMID 24325392, 2013). "Thus, anti-tumor functions of NK cells are suppressed by IL-6 and TGFβ1, and this is largely prevented by lenalidomide." (PMID 23982484, 2013). "In view of the capacity of minocycline to suppress tumor growth and malignant ascites formation, the minocycline-mediated blockade of IL-6 and its receptor system may be considered as an important contributing mechanism." (PMID 23593315, 2013). "Recent evidence found that IL-17 could enhance IL-6 production and subsequently promote tumor growth." (PMID 23305119, 2013). "IL-6 is discussed to be needed by the tumor cells in order to become Androgen independent." (PMID 23731674, 2013). "Effects on cancer stem cell compartment may be one of the mechanisms of tumor promotion through IL-6." (PMID 23593346, 2013). "Furthermore, IL-6–silencing vectors significantly inhibited TRAMP-C1 and HR tumor regrowth and invasion, which was associated with attenuated expressions of angiogenic factors and STAT3 activation." (PMID 23806095, 2013). "Therefore, we suggest activation of STAT3 signaling and angiogenesis after irradiation was reported to be responsible for resistance to treatment and tumor regrowth after irradiation triggered by IL-6." (PMID 23561329, 2013). "Hence, these results convincingly indicate that expression of IL-6 in the HY-PDT-treated cells was responsible for facilitating inflammation leading to tumor cell death." (PMID 23807226, 2013). "Our original hypothesis to test the tumor suppressive or promoting nature of BMP on fibroblasts was bolstered by the induction of IL-6." (PMID 23840733, 2013). "IL-6 is a mediator with dual activity in tumor growth and metastatic processes." (PMID 23552194, 2013). "For these reasons, Il-6 has been evaluated as a therapeutic target for several cancers, and early studies indicate that blocking Il-6 may lead to disease stabilization due to reduced tumor inflammatory infiltration and tumor angiogenesis." (PMID 23520493, 2013). "Therefore, in this study, we introduced a STAT3 activator, IL-22, that exhibits a tumor enhancement mechanism similar to IL-6." (PMID 23379788, 2013). "Moreover, IL-6 has been reported to increase in a variety of tumors, and contributes to aggressive tumor growth and resistance to treatment." (PMID 23806095, 2013). "TNFα, IL-6 and IL-17 are important links between chronic inflammation and tumor development." (PMID 23937962, 2013). "To test whether the induction of proinflammatory cytokines was required for the promotion of tumor cell invasion, we neutralized the endogenous IL-6 in the Gα12-overexpressed HSC-3 cells and examined the tumor cell invasiveness via transwell invasion assays." (PMID 23762476, 2013). "When 4T1 cells were inoculated into the mammary pad of interleukin -1 receptor (IL-1R)-deficient mice, the levels of cytokines, including IL-6, TNFα and MCP-1, in the tumor tissue were significantly reduced and both tumor progression and lung metastasis were reduced." (PMID 23527025, 2013). "In conclusion, IL-6, IL-8, sM-CSF and sG-CSF may indirectly promote tumor growth, progression and metastasis by changing the leukocyte populations in the blood and the tumor microenvironment." (PMID 23599759, 2013). "Rate of interleukin-6 positive staining by degree of tumor differentiation." (PMID 23593346, 2013).